ERBB4 (erb-b2 receptor tyrosine kinase 4)
Diseases named in the same sentence as ERBB4 in open-access papers (continued):
Sharing a sentence is not in itself a finding about the gene and the disease.
cancer (continued). "Thus, it appears that ERBB4 can mediate antagonistic functions in human cancer depending on the presence of different ERBB4 isoforms and the biological context." (PMID 26745281, 2016). "In addition, in xenografts model, ErbB4 mediated apoptosis was shown to be essential for the antitumor effect of tamoxifen and cancer patients with ErbB4 expression responded very well with tamoxifen therapy." (PMID 25538945, 2014). "In addition to known cancer driver genes such as ERBB2 (6% of cases), NRAS (3%), MET (3%), PIK3CA (1%), AKT2 (1%), TSC1 (1%), and ERBB4 (1%), several putative cancer genes were identified, such as PTPRC, SYNE2, GRIN2A, and CDH10." (PMID 24576404, 2014). "Interestingly, different cancer tissues and cell lines seem to predominantly express cleavable ErbB4 isoforms, and down-regulation of ErbB4 expression in ER-positive breast cancer cells with ribozymes or siRNAs reduces growth." (PMID 22761786, 2012). "Among different EGFR family members, the role of ErbB4 in cancer is probably the least understood." (PMID 21364581, 2011). "In addition, other well-known cancer-associated genes (including VEGFA, DUSP9 and ERBB4) were also selectively validated as exhibiting consistently disrupted expression patterns in most of the ccRCC samples profiled." (PMID 21253009, 2010). "Inhibitors targeting ERBB4 may be broadly applicable as therapeutic agents in majority of cancers." (PMID 36185201, 2022). "Interestingly, some synthetic (these mutations have not been identified in cancer patients as of yet) constitutively activating ERBB4 mutations, such Q646C and I658E, have been demonstrated not to promote growth, or even promote apoptosis, in vitro." (PMID 36860695, 2022). "Moreover, hundreds of somatic mutations in ERBB4 have been reported in different cancer types that are dispersed throughout the ERBB4 primary sequence in the absence of obvious mutation hotspots." (PMID 36860695, 2022). "However, the role of ERBB4 in human cancer is still debatable." (PMID 33732282, 2021). "The epidermal growth factor receptor (EGFR) kinase family consists of four receptors [ErbB1/EGFR, ErbB2/human epidermal growth factor receptor (HER) 2, ErbB3, and ErbB4] that play a crucial role in cell proliferation, differentiation, and motility and may lead to cancer development." (PMID 36045702, 2021). "We used publically available data from the cancer cell line encyclopaedia (CCLE) database to search for mutations in EGFR, ERBB2, ERBB3, ERBB4, KRAS and BRAF that might predispose to a different response to anti-HER2 therapies or PI3K or MAPK pathway inhibition." (PMID 33933113, 2021). "In addition, evidence showed that higher KIF5B and ERBB4 promoted cancer cell proliferation." (PMID 33441952, 2021). "In addition to a global view on ERBB3/ERBB4 signaling, our data create potential opportunities for follow-up studies to promote a better mechanistic understanding and explore potential links to cancer biology." (PMID 26745281, 2016). "Thus, the expression of ERBB2, ERBB3 and ERBB4 in EGFR driven cancer may be important to predict the outcome of TKI treatment." (PMID 23758840, 2013). "These overlap with cancer-specific ERBB2 and nuclear ERBB4 programs, as well as the downregulation of ERBB2/ERBB4 signaling." (PMID 41009685, 2025). "This analysis revealed upregulation of ERBB growth factor signaling to cancer cells post treatment, with increased communications received via all ERBB growth factor receptors (EGFR/ERBB1, HER2/ERBB2, HER3/ERBB3, and HER4/ERBB4)." (PMID 40341770, 2025).
cancer (continued). "Ibrutinib, developed primarily as a BTK inhibitor, exhibits nanomolar affinity for ERBB4 and has been shown to suppress cell growth and MEK and ERK signaling in cancer cell lines." (PMID 41256885, 2025). "A population-wide examination of TT and LN single cells found that primary cancer overexpresses NOTCH2, NOTCH2NL, KIF5B, and ERBB4 but that metastatic cancer overexpresses CDK12, ERBB2, and CLDN11." (PMID 37322261, 2024). "The current study focused on the effects of chrysophanol on cell motility and cancer metabolism in CRC via the KITENIN and ErbB4 pathways, and the results provide a new perspective on the previously demonstrated anticancer effects of chrysophanol." (PMID 39030594, 2024). "Our analysis highlighted that miR-19b, -146a, -186, -193b, and -203 share the target ErbB4, a member of the ErbB receptor family, also known as the EGF receptor family, which is involved in human cancer." (PMID 37371814, 2023). "Other transcription factors (TP73, ERBB4, TBX5 and RUNX3) detected variations across cell lines, with TP73 being notably upregulated in four cancer lines except for SqCC/Y1." (PMID 35000271, 2022). "Among newly identified genes, eleven other cancer targets were detected: MPL; ERBB4; VHL; FGFR3; KIT; KDR; PTEN; KRAS; PTPN11; ERBB2; and SMARCB1." (PMID 35621644, 2022). "Accordingly, the receptor tyrosine kinase Her4/ErbB4, an EGFR family member, is upregulated in several cancers including OS." (PMID 34294128, 2021). "The prognostic value of ERBB4 was an independent external validation in the cohort [TMB and Immunotherapy (MSKCC, Nat Genet 2019)] in cBioPortal of Cancer Genomics, according to the analysis herein." (PMID 34620079, 2021). "EGFR (also known as ErbB1 and HER1), ERBB2 (HER2/neu and HER2), ERBB3 (HER3), and ERBB4 (HER4), members of the (EGFR)/(ERBB) family, are known among the most important cancer molecular targets." (PMID 34803458, 2021). "Previous studies have been reported that NRG1 played important roles in cancers by directly binding to ERBB3 or ERBB4 and ERBB3 or ERBB4 interacts with ERBB2 or ligand-receptor, leading to receptor phosphorylation and signal cascade activation." (PMID 34531912, 2021). "ERBB4 has been reported as an important regulator of the PI3K/AKT signaling pathway to enhance the stem cell activity, angiogenesis, and proliferation of cancer cells." (PMID 34774079, 2021). "The ERBB4 p.His374Gln missense, described in ALS and cancer patients, was identified in one sALS and one unrelated fALS patient." (PMID 32397312, 2020). "Many of these cancer types also express erbB3, a second NRG1 receptor that is functionally distinct from erbB4." (PMID 31291965, 2019). "When bound by ligands like neuregulin, ERBB4 activates numerous downstream pathways, including Ras/MAPK/ERK and PI3K/AKT signaling (via mTOR), to regulate both normal cellular processes and cancer development and progression." (PMID 28042953, 2017). "Dacomitinib (PF-00299804) is a tyrosine kinase inhibitor (TKI), which is predicted to only be effective in cancers where the targets of this drug (EGFR, ERBB2, ERBB4) are abnormally active." (PMID 28394918, 2017). "Further, quantitative proteomic analysis and data from the cancer genome atlas revealed that ACLY, an enzyme key for de novo lipogenesis, was negatively correlated with ERBB4." (PMID 26701850, 2016). "Recently, we identified that KITENIN/ErbB4-Dvl2-c-Jun axis is an unconventional EGFR-independent downstream signal of EGF and mediates the invasiveness and tumorigenesis of cancer cells." (PMID 26371759, 2015).
cancer (continued). "The erbB receptors, including the epidermal growth factor receptor (EGFR), erbB2 (also known as HER2/neu), erbB3 (or HER3), and erbB4 (or HER4), are often aberrantly activated in a wide variety of human cancers." (PMID 24886126, 2014). "The epithelial growth factor receptor (EGFR) family consists of four members, EGFR (HER1), ErbB2 (HER2), ErbB3 (HER3), and ErbB4 (HER4), and has been shown to play an important role in metastasis and tumorigenesis in many types of human cancers." (PMID 22479527, 2012). "Thereafter, we and other investigators confirmed the inhibitory effects of EGCG on other RTKs including erbB3/Her3, erbB4/Her4, IGFR, PDGFR, FGFR, and VEGFR employing a variety of cancer cell lines derived from different organs." (PMID 21274257, 2011). "The ErbB tyrosine kinase superfamily, comprising the epidermal growth factor receptor (EGFR; also known as ErbB1/HER1), ErbB2 (HER2/neu), ErbB3 (HER3) and ErbB4 (HER4), plays important roles in cancer development and progression." (PMID 21789172, 2011). "These miRNAs target the tumour suppressor genes, PTEN, TP53INP1 and TP53INP2, and other proteins involved in cancer development and progression, such as BCL2L2, ERBB4, MAPK9, MCL1, MYCN, VEGFA and VEGFR1." (PMID 20668671, 2010). "Network analysis pinpointed specific regulatory hubs, such as SOX2 and SERPINE1 for HPV16, and ERBB4 and GLI1 for HPV18, which may facilitate malignant tumor growth by disrupting metabolic, keratinization, and extracellular matrix pathways." (PMID 41993883, 2026). "ERBB4, a member of the ErbB/HER family, has been detected in malignant tumors." (PMID 38987777, 2024). "In the current study, we examined whether chrysophanol suppresses KITENIN-mediated cancer progression, and if this effect occurs via disruption of the KITENIN/ErbB4 functional complex." (PMID 39030594, 2024). "Moreover, by using the same evaluation criteria, we identify new biomarkers whose impact on drug response spans multiple cancers, including SALL4, B2M, BAP1, CCDC6, ERBB4, FOXA1, GRIN2A, and PTPRT." (PMID 39083502, 2024). "When patients with cancer are given pan-ERBB/HER inhibitors, ERBB4/HER4/ALS19 function is attenuated, but any feedback upregulation of NRG1 should it occur cannot overstimulate ERBB1/2/3 because the pan-ERBB/HER inhibitor diminishes the function of these other ERBBs." (PMID 38369520, 2024). "RAC2 also showed upregulation of proliferative pathways, including signalling by NTRK2/TRKB, characterised by overexpression of the PIK3CA gene, and signalling by ERBB2 in cancer, as reflected by elevated serum concentrations of SHC1, ERBB4, EGFR and ERBB2, compared with RAC3." (PMID 39401856, 2024). "In addition to the receptors FGFR1, FGFR4 and ERBB4, the main effector AKT1 and its downstream effectors, MTOR, GSK3B, p21, WEE1, BAD and CREB5, which mediate cancer cell growth and progression, also exhibited marked changes in HPV-ind CCs." (PMID 38253702, 2024). "Approximately 0.15–0.5% of cancers harbor NRG1 fusions that upregulate NRG1 activity and hence that of the cognate ERBB3/ERBB4 (HER3/HER4) receptors; abrogating this activity with small molecule inhibitors/antibodies shows preliminary tissue-agnostic anti-cancer activity." (PMID 38369520, 2024). "On the contrary, decreased levels of neuregulin 1 (NRG1), a direct ligand of ERBB3 and ERBB4 tyrosine kinase receptors, which activate ERBB receptors, could be responsible for the inhibition of cancer cell growth." (PMID 37834191, 2023). "Interestingly, the activation of ERBB4 by ligands (NRG1, HBEGF) has been shown to inhibit proliferation and/or promote differentiation in human breast normal and cancer cell lines." (PMID 35664762, 2022). "Compared to Del-c1 and c3, the majority of cancer genes were deleted by DEL-c2, such as CDKN2A (207/528), FHIT (133/528), KDM6A (42/528), RB1 (27/528), FAT1 (23/528), NFE2L2 (13/528), ERBB4 (20/528), CUL3 (11/528), PTEN (9/528), ZNF750 (13/528) and NOTCH1 (8/528)." (PMID 36272974, 2022).
cancer (continued). "However, this study also shows unexpected up-regulation of crucial genes and kinases (e.g., ERBB4, PLCβ4, PRKAR2B, and PDGFA) whose roles in cancer development and progression are crucial." (PMID 36430510, 2022). "Of note, the eQTL-based shared supersets included lipid and glucose metabolisms and nuclear signaling by ERBB4 (also known as human epidermal growth factor receptor 4 [HER4]), which play critical roles in carcinogenic progression of specific cancers, including BC." (PMID 34572592, 2021). "Other ERBB-family-receptors (ERBB2, ERBB3, and ERBB4) were barely expressed in basal cancers, whereas non-basal BLCA showed increased mRNA expression of different ERBBs." (PMID 32978523, 2020). "On the contrary, EPHB2, ERBB4, FGFR1, PDGFRA, KDR, and FLT1 genes showed deletion in cancer cells." (PMID 32038722, 2019). "In patient P4, two of four malignant ascites-emerging clones may be targetable by inhibitors against BRAF (e.g. Vemurafenib), TEP1, ERBB4, PIK3CA, HDAC9, or FYN." (PMID 26811494, 2016). "ErbB4 and pErbB4 were nearly absent in glandular epithelial cells of colorectal mucosa adjoining cancer tissue." (PMID 25416285, 2014). "The role of nuclear ErbB-4 ICD is still ambiguous but has been shown to be involved in both shorter patient survival and improved patient response to tamoxifen therapy for estrogen receptor-α positive cancers." (PMID 22520625, 2012). "Specifically, we focused on four previously-studied, targeted anti-cancer drugs for which our model includes primary targets and significant off-targets: trametinib (MEK inhibitor), alpelisib (PI-3Kα inhibitor), neratinib (EGFR/ErbB2/ErbB4 inhibitor), and palbociclib (CDK4/6 inhibitor)." (PMID 40880521, 2025). "However, the biologic role of ERBB4 and its potential as a target for cancer drugs has not been clearly identified." (PMID 26907936, 2016). "Finally, ranking cancer driver mutations by their correlation with glutamine reveals that KRAS and ERBB4 have the strongest negative correlation (indicating that mutation is associated with a reduction of glutamine), and PRCC, JUN and PIK3CA mutations rank highly with an accumulation of glutamine." (PMID 36321551, 2022). "Whilst the use of such cell lines may not be an entirely accurate representation of in vivo cancer cell behavior, these cells provided a good model for studying the effect of such inhibition as they express both endogenously activated EGFR and ERBB4." (PMID 30044378, 2018). "Historically, EGFR inhibitors have not been effective against KRAS-mutant cancers; however, second generation inhibitors have shown promise in treating both KRAS- and EGFR-mutant tumors by targeting all members of the ErbB family of proteins (EGFR/ERbB1, HER2/ErbB2, HER3/ErbB3, HER4/ErbB4)." (PMID 36674513, 2023). "However, the biological function of ERBB4 and its potential as a cancer drug target have not been explicitly described, and we also hope that patients suffering from TNBC with ERBB4 overexpression would benefit from further clinical trials on receptor tyrosine kinase (RTKs)." (PMID 36313438, 2022). "In addition, we discovered that erbB4 regulates the phosphorylation of two molecules—with-no-lysine kinase 1 (WNK1), a kinase that is phosphorylated at Thr60 by Akt, and heat shock protein 60 (HSP60)—that promote tumorigenesis in other cancer types." (PMID 31291965, 2019).
psychiatric disorder (17 papers, 2015 to 2024). A disorder characterized by behavioral and/or psychological abnormalities, often accompanied by physical symptoms. "Taken together, our study linked ErbB4 physiological function with NE system homeostasis and demonstrated the pathogenic effect of ErbB4 dysregulation in NE neurons in mania-associated psychiatric diseases." (PMID 30179154, 2018). "Mutations (loss of function) and other alterations of the ERBB4/HER4 receptor (also known as ALS19) have been linked to several neurological and psychiatric disorders, including ALS and schizophrenia." (PMID 38369520, 2024). "Like Erbb4 KO mice, Nrg2 KOs performed abnormally in a battery of behavioral tasks relevant to psychiatric disorders." (PMID 34072341, 2021). "The paper and experiments are well written and the results are very interesting and will likely be very valuable as a reference for other studies examining the role of ErbB4 in psychiatric disorders." (PMID 32354758, 2020). "Moreover, we confirm and expand on behavioral deficits observed in ErbB4 KOs relevant to psychiatric disorders, including increased locomotor activity, cognitive-related impairments, and elevated motivation/willingness to retrieve food rewards." (PMID 32354758, 2020). "In conclusion, our results showing that restricted post-adolescent deletion of NMDAR from a relatively large neuronal population of ErbB4-positive neurons does not affect behavior is once again emphasizing the role of neurodevelopmental impairment in the emergence of several psychiatric disorders." (PMID 34899420, 2021). "NRG1/erb-b2 receptor tyrosine kinase 4 (ERBB4) signaling in DA-ergic axonal projections modulates DA homeostasis, whereas NRG1/ERBB4 signaling in both GABA-ergic interneurons and DA neurons in the midbrain contribute to the modulation of animal behaviors relevant to psychiatric disorders." (PMID 34072341, 2021).
adenocarcinoma (12 papers, 2009 to 2025). A common cancer characterized by the presence of malignant glandular cells. "Significant differences can be found in the mutation rate of EGFR (60.9% vs 11.9%), KRAS (12.2% vs 25.0%), STK11 (1.5% vs 11.9%), FGFR3 (2.4% vs 0.0%) and ERBB4 (1.2% vs 6.1%) between adenocarcinoma in our cohort and TCGA-LUAD data (all p < 0.001)." (PMID 38496837, 2024). "Multiparous transgenic female mice expressing NRG1, a ligand for ERBB3 and ERBB4, under control of the MMTV promoter also develop adenocarcinomas in the mammary glands at a median age of 12 months, suggesting ErbB4 to be contributing to neuregulin-induced carcinogenesis." (PMID 25516216, 2014).